LINC00520 (long independently transcribed non-coding RNA 520)
Diseases named in the same sentence as LINC00520 in open-access papers (continued):
Sharing a sentence is not in itself a finding about the gene and the disease.
cancer (16 papers, 2016 to 2025). A tumor composed of atypical neoplastic, often pleomorphic cells that invade other tissues. "LINC00520 is a lncRNA that is widely expressed in various tissues and has been linked to the clinicopathological characteristics of 11 cancers; however, its role in osteoblast differentiation has not been explored." (PMID 37516879, 2023). "Nine single‐nucleotide polymorphisms (SNPs) on LINC00520 genotyping were performed in 504 BC patients and 505 cancer‐free controls in Chinese Han population to study the relationship between LINC00520 polymorphism and BC susceptibility." (PMID 31997582, 2020). "LINC00520 is generally highly expressed in cancer, however, a study has shown that LINC00520 is down-regulated in cSCC." (PMID 35309319, 2022). "Highly expressed LINC00520 is also closely related to the clinicopathological characteristics of cancer patients." (PMID 35309319, 2022). "In summary, LINC00520 can participate in the growth and development of cancer cells through sponging miRNAs." (PMID 35309319, 2022). "This article reviews the diagnostic and prognostic value of abnormally high expression of LINC00520 in cancer." (PMID 35309319, 2022). "The effect of LINC00520 on biological behaviors of cancer cells promoted us to further investigate its roles in GBM chemoresistance." (PMID 35945579, 2022). "Here, this article summarizes the abnormal expression pattern of LINC00520 in cancer and its potential molecular regulation mechanism and points out that LINC00520 can be used as a potential biomarker for cancer diagnosis, prognosis, and treatment." (PMID 35309319, 2022). "LINC00520 has been shown to up-regulate and modulate the malignant phenotype of tumor cells in some malignant tumors." (PMID 32466797, 2020). "Multiple studies suggest a strong correlation between LINC00520 and the clinicopathological features, prognosis, and therapy response in cancer patients, indicating the significant potential of LINC00520 in cancer diagnosis, prognostic prediction, and treatment." (PMID 38284893, 2024). "In summary, we hypothesize that LINC00520 may be contribute to tumorigenesis and cancer development of DLBCL by PI3K/AKT and JAK/STAT signaling pathways." (PMID 38284893, 2024). "LINC00520 can predict a poor prognosis for a variety of cancers." (PMID 35309319, 2022). "LINC00520 has great potential in cancer diagnosis, prognostic evaluation, and treatment." (PMID 35309319, 2022). "The current study found that LINC00520 is abnormally expressed in a variety of cancers." (PMID 35309319, 2022). "In recent years, LINC00520 has been shown to play a key role in various cancers." (PMID 35309319, 2022). "As an oncogene, LINC00520 was highly expressed in numerous types of cancers." (PMID 34250091, 2021). "Additionally, LINC00520 could serve as a possible indicator and a hopeful treatment target for DLBCL.ANKRD10-IT1 has been utilized as a diagnostic or prognostic indicator in various cancer types." (PMID 38284893, 2024). "The validation results were highly in great agreement with those in microarray, and the expression tendency of HOTAIR, TINCR, LINC00511, LINC00520, MEG3, and ZNF667-AS1 was also consistent with literature reports in other carcinomas." (PMID 31196171, 2019). "As expected, our microarray profiles identified several lncRNAs, which were aberrantly expressed in human cancer, such as LOC100190940, LOC100506178, H19, PVT1, VPS9D1-AS1, Linc00520, Linc00675, GNG12-AS1 CDKN2B-AS1, and CCAT1." (PMID 29523145, 2018).
tumor (7 papers, 2020 to 2023). "In NSCLC, high LINC00520 levels are significantly associated with advanced tumor stage and positive lymph node metastasis." (PMID 35309319, 2022). "In CRC, the high expression of LINC00520 is significantly associated with increased tumor size, lymph node metastasis, and advanced TNM stage." (PMID 35309319, 2022). "Increased LINC00520 expression was significantly associated with advanced tumor stage and shorter survival time in NSCLC patients." (PMID 35309319, 2022). "Overexpression of LINC00520 inhibits the expression of downstream tumor suppressor miR-577, up-regulate POSTN, and promote the activation of ILK/AKT/mTOR pathway." (PMID 37901333, 2023). "The orthotopic xenograft model was established and the results indicated that the volume of tumor xenografts in vivo was markedly inhibited by TMZ treatment after the silencing of LINC00520 (P < 0.001)." (PMID 35945579, 2022). "In xenograft tumor models, the silencing of LINC00520 and the overexpression of miR-195 can inhibit the tumor formation of HNSCC xenografts after radiotherapy." (PMID 35309319, 2022). "LINC00520 can competitively bind 10 miRNAs to promote tumor cell proliferation, invasion, and migration." (PMID 35309319, 2022). "The expression of LINC00520 is significantly related to the clinicopathological characteristics and prognosis of tumor patients and is also related to the sensitivity of HNSCC to radiotherapy." (PMID 35309319, 2022). "Through the LINC00520/miRNA/mRNA axis, LINC00520 directly or indirectly regulates the biological behaviors of tumor cells, such as epithelial-mesenchymal transition (EMT), proliferation, invasion, metastasis, apoptosis, etc." (PMID 35309319, 2022). "Using bioluminescence imaging system, we found that the volume of intracranial tumor xenografts were markedly reduced by the silencing of LINC00520, while a significant progression in tumor growth was observed in the si-NC group (P < 0.001)." (PMID 35945579, 2022). "In PTC, the high expression of LINC00520 is significantly related to increased tumor size, lymph node metastasis, and advanced TNM stage of PTC patients." (PMID 35309319, 2022). "Altogether, these results suggest that LINC00520 plays a tumor suppressive role in cSCC by targeting EGFR." (PMID 32462404, 2020). "Knockdown group of LINC00520 displayed the inhibition of tumor growth compared to the control group between 16 and 28 days." (PMID 32466797, 2020). "Downregulation of LINC00520 has been noted in A431 cSCC cell line, compared to NHEKs, and overexpression of LINC00520 in A431 cells results in suppression of tumor growth and lymph node metastasis." (PMID 32462404, 2020). "Knockdown of LINC00520 can significantly inhibit cell proliferation and tumor growth." (PMID 37901333, 2023). "LINC00520 is upregulated in BC and promotes tumor invasion and metastasis." (PMID 35309319, 2022). "Here, this article provides a detailed review of the research progress, molecular mechanism, and clinical significance of LINC00520, aiming to clarify the important role of LINC00520 in tumor diagnosis and prognosis, and provide clues for the future research of LINC00520." (PMID 35309319, 2022). "However, in cSCC, LINC00520 overexpression can inhibit tumor growth and lymph node metastasis." (PMID 35309319, 2022). "Knockdown of LINC00520 can inhibit the proliferation of NPC cells in vitro and tumor growth in vivo, and exert a tumor suppressor effect." (PMID 35309319, 2022).
LINC00520 also shares sentences with these, for which no sentence is quoted: atherosclerosis (2 papers); laryngeal squamous cell carcinoma (2); diabetes (1); endothelial dysfunction (1); gastric cancer (1); glioblastoma (1); Hyperglycemia (1); hypertensive disorder (1); metabolic disease (1); non-small cell lung carcinoma (1); Obesity (1); osteosarcoma (1); renal cell carcinoma (1); skin squamous cell carcinoma (1).